ACY1 (aminoacylase 1)
Description:
Aminoacylase involved in the hydrolysis of N-acetylated and N-formylated amino acids. May act sequentially with APEH in the degradation of N-acylated peptides: APEH first cleaves N-acylaminoacids from N-acylated peptides, then ACY1 further hydrolyzes the N-acylaminoacid into free aminoacid and a carboxylate.
Synonyms: ACY-1; ACY1D; HEL-S-5
Tractability: Small molecule: a structure with a bound ligand is known. PROTAC: ubiquitination databases record sites on it; its protein half-life has been measured.
Gene: Protein-coding gene on chromosome 3 (51,983,047 to 51,989,205, forward strand). Ensembl gene ENSG00000243989.
Subcellular location: Cytoplasm
Subcellular location (Human Protein Atlas): Vesicles
Pathways (Reactome):
Disease: Defective ACY1 causes encephalopathy
Drug ADME: Paracetamol ADME
Metabolism: Aflatoxin activation and detoxification
Gene Ontology:
Molecular function: aminoacylase activity; identical protein binding; protein binding; formylmethionine deformylase activity; hydrolase activity
Biological process: amino acid metabolic process
Cellular component: extracellular exosome; cytosol; cytoplasm
Genetic constraint (gnomAD): Loss-of-function variants: 39 observed, 56.6 expected, observed/expected ratio (o/e) 0.69, 90% interval 0.53 to 0.9. The upper end of that interval is the gene's LOEUF score, 0.9, which puts it in group 3 of 6, group 1 being the genes least tolerant of losing a copy. Missense variants: 484 observed, 566.59 expected, observed/expected ratio (o/e) 0.85, 90% interval 0.79 to 0.92. Synonymous variants: 177 observed, 213.22 expected, observed/expected ratio (o/e) 0.83, 90% interval 0.73 to 0.94.
Gene-disease validity (ClinGen):
ClinGen rates the evidence that ACY1 causes each of these diseases.
aminoacylase 1 deficiency (autosomal recessive): Definitive. Aminoacylase 1 deficiency (ACY1D) is an inborn error of metabolism marked by a characteristic pattern of urinary N-acetyl amino acid excretion and neurologic symptoms.
Homologues: Orthologues: chimpanzee ACY1 (98% identical), macaque ACY1 (90% identical), rabbit ACY1 (89% identical), pig ACY1 (88% identical), rat Acy1 (88% identical), mouse Acy1 (85% identical), guinea pig ACY1 (83% identical), zebrafish acy1 (61% identical), tropical clawed frog acy1 (55% identical), Drosophila melanogaster CG6465 (48% identical), Caenorhabditis elegans C06A6.4 (47% identical), Caenorhabditis elegans C10C5.5 (46% identical), and 7 more. Paralogues in human: CNDP1 (19% identical), PM20D1 (18% identical), CNDP2 (17% identical).